FGF23 (fibroblast growth factor 23)
Diseases named in the same sentence as FGF23 in open-access papers (continued):
Sharing a sentence is not in itself a finding about the gene and the disease.
iron deficiency (continued). "In addition, we previously showed that inhibition of FGF23 signaling rescues renal anemia and iron deficiency in mice with CKD induced by 5/6 nephrectomy." (PMID 35813388, 2022). "Several murine studies demonstrate that iron deficiency potently induces Fgf23 mRNA expression." (PMID 35237863, 2022). "Importantly, we reported that inhibition of FGF23 signaling by the use of an antagonist rescues anemia, and ameliorates iron deficiency and inflammation in mice with CKD." (PMID 35813388, 2022). "Therefore, FGF23 antagonists are strong candidates for the treatment of renal anemia, iron deficiency and associated inflammation, and have the potential to attenuate Klotho deficiency." (PMID 35813388, 2022). "In patients with iron deficiency or with acute inflammatory processes, an increased production of FGF23 was detected simultaneously with an increase in the cleavage of the same molecule; in this case a greater quantity of fragments was found in the plasma than in intact molecules." (PMID 36440231, 2022). "However, many other factors play a critical role in the development of renal anemia, such as iron deficiency, inflammation, and elevated fibroblast growth factor 23 (FGF23) levels." (PMID 35813388, 2022). "Indeed, despite severe elevations in serum FGF23, dietary Pi restriction limited functional iron deficiency." (PMID 35302487, 2022). "Recently, iron deficiency has been identified as a novel stimulus of FGF23 production." (PMID 35237863, 2022). "The marked reduction in maternal and neonatal total-FGF23 concentrations after antenatal iron supplementation is in keeping with previous studies and is likely caused by a reversal of hypoxia and/or EPO-driven FGF23 gene expression in osteocytes that occurs in iron deficiency." (PMID 33675347, 2021). "Since iron deficiency increases FGF23 expression, this gene-environment interaction explains why adult-onset ADHR may be unmasked by iron deficiency and may be cured with (oral) iron supplements alone." (PMID 33815294, 2021). "Altogether these results suggest that furin may be the main PC responsible of FGF23 processing under iron deficiency." (PMID 34149625, 2021). "Therefore, first, pre-existing iron deficiency upregulates the transcription of FGF23 through activated hypoxia-inducible factor 1 alpha and/or erythropoietin production." (PMID 34901334, 2021). "However, iron-deficiency resulted in increased in circulating C-terminal FGF23 only in control mice, although both genotypes showed an increase in circulating intact FGF23." (PMID 34149625, 2021). "The results obtained in the context of iron deficiency raised the question as to whether, under normal conditions, FGF23 may also be cleaved by another PC that would be downregulated in osteocytes following iron deficiency." (PMID 34149625, 2021). "Under conditions of iron deficiency furin is responsible for this process, while following single injection of rhEPO or IL-1β, additional proteases may be involved in FGF23 processing." (PMID 34149625, 2021). "Moreover, HIF1α is believed to be involved in altered FGF23 cleavage seen in inflammation and iron deficiency." (PMID 33716961, 2021). "Injection of recombinant human EPO in mice resulted in increased Fgf23 mRNA and cFgf23, but only marginally increased iFgf23, indicating that production and cleavage of FGF23 are directly linked, as observed in inflammation and iron deficiency." (PMID 33716961, 2021). "In recent years, iron deficiency has been identified as an important regulator of FGF23." (PMID 32512806, 2020). "However, to date, we still know very little about modifying genes and how exactly iron deficiency stimulates FGF23 mRNA expression." (PMID 31834957, 2020). "Interestingly, there is also evidence for a reverse causal relationship, i.e., that FGF23 contributes to iron deficiency by increasing hepcidin levels as indicated by experimental iFGF23 blockage." (PMID 32823844, 2020).
iron deficiency (continued). "Recent studies have shown that iron deficiency could increase the FGF23 degradation, and administration of parenteral iron products, such as ferric carboxy-maltose increases FGF23 level." (PMID 33198660, 2020). "Chronic overexpression of EPO can lead to iron deficiency, so to determine whether the iron deficiency was causing the elevated FGF23, mice were given iron dextran." (PMID 32982979, 2020). "Iron deficiency increases FGF23 mRNA expression and recent evidence suggests that the recurrent, late‐onset, or waxing‐waning hypophosphatemic phenotype may be linked to synchronous variations in iron status." (PMID 31834957, 2020). "Similarly, a functional iron deficiency via a treatment of mice with hepcidin also increased bone Fgf23 mRNA expression." (PMID 32982979, 2020). "Treatment of iron deficiency in CKD mice resulted in a significant decrease in whole bone FGF23." (PMID 30971944, 2019). "Co-existence of iron deficiency or rhEPO administration still influence FGF23 secretion in CKD." (PMID 30971944, 2019). "Due to co-existence of anemia, erythropoiesis-related factors might influence the iron deficiency-FGF23 pathway." (PMID 30971944, 2019). "In the current study, we have shown that, in the general population, iron deficiency is a major determinant of FGF23 levels, implicating that iron deficiency could potentially be an easily modifiable driver of high FGF23 levels." (PMID 31170159, 2019). "In contrast to functional iron deficiency and its mediators regulating FGF23 production, absolute iron deficiency has been shown to regulate FGF23, along with clinical studies demonstrating an association between FGF23 and erythropoiesis." (PMID 31461904, 2019). "Furin plays an important role in regulation of FGF23 cleavage in iron deficiency and inflammation, whereas under conditions of high EPO GalNT3 inhibition might augment cleavage." (PMID 30971944, 2019). "Our findings suggest that FGF23 could be involved in the pathophysiology of iron-deficiency–and EPO-mediated mortality in the population." (PMID 31170159, 2019). "Our findings suggest that FGF23 could be involved in the association between functional iron deficiency and increased EPO levels and death." (PMID 31170159, 2019). "Interestingly, animal and human studies demonstrated that absolute and functional iron deficiency stimulates FGF23 production." (PMID 29740119, 2018). "One might speculate that an iron overload leads to a decrease in FGF-23 production in an opposite direction to the effect of iron deficiency." (PMID 29726397, 2018). "Furthermore, subgroup analyses showed that a significant association between high FGF23 levels and the development of anemia was evident in patients with iron deficiency and high inflammatory status." (PMID 29740119, 2018). "FGF23 is a bone-derived hormone involved in calcium-phosphate homeostasis regulated by active vitamin D and phosphate, and more recently also noted to be stimulated by iron deficiency." (PMID 30537973, 2018). "Iron deficiency, an opposite condition to iron overload state, has been reported to be associated with elevated serum FGF-23 levels in patients with autosomal dominant hypophosphatemic rickets (ADHR), in the elderly population and in undernourished Gambian children." (PMID 29726397, 2018). "Likewise, FGF23 production stimulated by iron deficiency is coupled with increased cleavage maintaining normal circulating levels of the active iFGF23." (PMID 29073196, 2017). "In addition, iron deficiency is also known to stimulate fibroblast growth factor 23 (FGF23), a bone-derived phosphaturic hormone." (PMID 28878231, 2017). "Iron deficiency anaemia itself is associated with higher levels of FGF23 in laboratory and clinical studies, and so the degree of iron availability in participants may influence baseline levels of FGF23." (PMID 27852236, 2016). "Iron deficiency has been described to stimulate HIF1α leading to increased FGF-23 transcription." (PMID 23555610, 2013).
iron deficiency (continued). "The complex relationship between iron status and FGF23 regulation might potentially reflect both disturbed bone remodeling in iron deficiency, disturbed iron sensing and signaling and adaptive responses to iron deficiency." (PMID 24373521, 2013). "Furthermore an improvement in iron status, associated with iron supplementation in a population with endemic iron deficiency, is associated with a decrease in plasma FGF23." (PMID 23098062, 2012). "The bone-derived hormone fibroblast growth factor 23 (FGF23), the regulator of vitamin D and phosphate homeostasis, has been speculated to be implicated, given that anemia, iron deficiency and inflammatory conditions are all known to increase FGF23 expression levels in osteoblasts." (PMID 41751190, 2026). "Therefore, iron deficiency increases levels of FGF23 measured by C-terminal assays (cFGF23) that measure both full-length FGF23 and its C-terminal cleavage fragments, while the full-length FGF23 levels that are detected exclusively by intact FGF23 assays (iFGF23) remain unchanged." (PMID 38402503, 2024). "Therefore, correction of iron deficiency was associated with reduced FGF-23 production." (PMID 39684548, 2024). "Therefore, even when phosphorus load does not result in increased serum phosphorus or mild elevation of serum phosphorus occurs within the normal range, phosphorus load stimulates FGF23 secretion resulting in several adverse outcomes, including anemia and iron deficiency." (PMID 39666728, 2024). "However, whether excess FGF23 and/or Pi directly contribute to functional iron deficiency or skeletal muscle wasting is unknown, and direct actions of excess Pi on the liver have not been studied to date." (PMID 35302487, 2022). "However, in CKD, FGF23 proteolytic cleavage may be impaired, thus uncoupling iron deficiency-induced increased FGF23 transcription from its post-translational cleavage." (PMID 35237863, 2022). "In addition, iron-deficiency also induced increments of Hypoxia Inducible Factor 1α (HIF1α), and HIF1α itself could also boost FGF23 expression." (PMID 35629904, 2022). "Besides the propensity to accumulate phosphate as a driver for FGF23 increases, in addition to hyperparathyroidism, DMP1 suppression chronic inflammation, iron deficiency, and FGF23 resistance due to α-klotho deficiency have all been implicated in the exponential rise of FGF23 as CKD progresses." (PMID 35629904, 2022). "Therefore, in the absence of CKD, iron deficiency results in increased circulating concentrations of FGF23 fragments; however, in the presence of CKD, iron deficiency may increase concentrations of full-length FGF23." (PMID 35237863, 2022). "Such a trend could be hypothetically explained by associations between FGF23 and iron deficiency." (PMID 34258392, 2021). "In view of these observations, we induced iron-deficiency in control and Furinosb-/- mice by feeding them a low-iron diet in combination with repeated tail bleedings (i.e., ~70 μl every other week) for 14 weeks, before assessing the impact on FGF23 and phosphate metabolism." (PMID 34149625, 2021). "Hence, iron deficiency, by a yet unknown gene–environment interaction mechanism increases FGF23 expression, probably on a transcriptional and posttranslational level." (PMID 31834957, 2020). "Notably, we identified FGF23 as a potential mediator of iron-deficiency–and EPO-related mortality." (PMID 31170159, 2019). "Therefore, inflammation and iron deficiency promote not only FGF23 transcription but also cleavage." (PMID 30909513, 2019). "Additionally, other regulators of FGF23 expression and cleavage might develop under inflammatory conditions as inflammation-induced functional iron deficiency." (PMID 30971944, 2019).
iron deficiency (continued). "Finally, although we have strong evidence from the literature that FGF23 is a mediator in the association of iron deficiency and EPO with mortality, we cannot exclude that an unmeasured cause of mortality or alternative potential mediators have influenced the current results." (PMID 31170159, 2019). "However, the associations among FGF23 levels, iron deficiency and ferrotherapy in CKD patients remain unclear." (PMID 28475601, 2017). "Thus, high FGF23 levels may be accompanied by inflammation, resulting in the development of functional iron deficiency." (PMID 28475601, 2017). "However tempting the theory is, no studies have been conducted so far implying that the limitation of inflammation or the correction of iron deficiency could decrease the elevated plasma FGF23 concentrations in CKD." (PMID 27941640, 2016). "Additionally, inflammation and iron deficiency can contribute to the increase of plasma FGF23." (PMID 27941640, 2016). "The current hypothesis is that, in healthy individuals, iron deficiency stimulates FGF23 production whereby osteocytes couple increased production of FGF23 with increased cleavage to cFGF23 to maintain normal circulating levels of iFGF23, which is the biologically intact hormone." (PMID 26079688, 2015). "A recent study in rats has shown that iron deficiency had effects on Fgf23 gene expression similar to those of oxygen deprivation, suggesting a mechanism that iron deficiency may result in hypoxia resulting in an increased Fgf23 gene expression due to hypoxia-induced factors." (PMID 24258305, 2014). "Recent data suggest that iron deficiency may stimulate FGF23 transcription." (PMID 24373521, 2013). "However, under pathophysiological conditions, FGF23 production in other organs may be ramped up, including kidney in polycystic kidney disease, heart in cardiac pathologies, or bone marrow in iron deficiency anemia." (PMID 40483378, 2025). "Iron deficiency, one of the factors mainly responsible for anemia in CKD, has been found to be associated with elevated FGF-23 levels in the elderly with CKD and in kidney transplant patients." (PMID 39684548, 2024). "Therefore, whereas iron deficiency, increased erythropoietin, and anemia may contribute to higher FGF23 levels (with total FGF23 increased more so than intact FGF23), elevated FGF23, in turn, may contribute to decreased erythropoietin and impaired erythropoiesis." (PMID 37752381, 2024). "Similar to iron deficiency, both endogenous and exogenous EPO increases transcription through the cleavage of FGF23." (PMID 38732094, 2024). "Iron deficiency upregulates furin, a proprotein convertase that cleaves iFGF-23, by stabilizing HIF1-α, thereby leading to cleavage of FGF-23 into C-terminal cleavage fragments (c-FGF-23)." (PMID 39684548, 2024). "Therefore, iron deficiency in CKD patients could contribute to the increase in FGF23." (PMID 38732094, 2024). "Renal injury — as well as iron deficiency, inflammation, and anemia, which are often found in patients with CKD — also result in increased FGF23 production in bone." (PMID 38530370, 2024). "Other direct stimulators of FGF-23 include Lipocalin 2 (LCN2, a marker of inflammation and an iron transporter), reduced oxygenation, iron deficiency, and Epo." (PMID 39684548, 2024). "Research on the interaction between FGF23 and iron metabolism originated from clinical observations in patients with autosomal dominant hypophosphatemic rickets (ADHR) and iron deficiency." (PMID 38732094, 2024). "For example iron deficiency, a common finding in HF, upregulates FGF-23 production but also increases cleavege which results in higher levels of c- terminal FGF-23 while the intact form of FGF-23 stays the same." (PMID 37749114, 2023). "Nevertheless, patient 2 suffered from anemia due to iron deficiency; for this, an interconnection with FGF-23 has previously been described, whereby low serum iron levels correlate with higher serum FGF-23." (PMID 37432176, 2023).
iron deficiency (continued). "In the setting with normal kidney function, iron deficiency, and EPO increase the production and cleavage of FGF23." (PMID 36831276, 2023). "To examine FGF23 inflammatory actions in vivo, we explored pathologic FGF23-FGFR4 signaling and its role in functional iron deficiency." (PMID 35302487, 2022). "In CKD patients, iron deficiency and increased blood erythropoietin (EPO) levels can stimulate the expression of FGF23." (PMID 34901023, 2021). "The same group has shown in the murine 5/6 nephrectomy model that FGF23 contributes to anemia in CKD by suppressing EPO, inducing iron deficiency, and increasing apoptosis." (PMID 32823844, 2020). "To date, clinical implications of iron deficiency and high EPO levels in the general population, and the potential downstream role of FGF23, are unclear." (PMID 31170159, 2019). "Mechanistically, inflammation and iron deficiency increase the activity of the hypoxia-inducible factor 1-alpha (HIF-1α) signaling, thereby augmenting Fgf23 transcription." (PMID 30909513, 2019). "Hence, in the current study, we investigated whether iron deficiency and EPO influence FGF23 levels, whether iron deficiency and elevated EPO levels are associated with an increased risk of death, and whether such associations could be explained by variation in FGF23 levels." (PMID 31170159, 2019). "Currently, the clinical implications of iron deficiency and high EPO levels in the general population, as well as the potential downstream role for FGF23, are unclear." (PMID 31170159, 2019). "We subsequently found that the associations between functional iron deficiency—reflected by low TSAT or high sTfR levels—and mortality were mediated by FGF23." (PMID 31170159, 2019). "Functional iron deficiency and EPO were associated with an increased risk of death in the general population, and FGF23 explained a substantial part of these associations." (PMID 31170159, 2019). "Iron deficiency and elevated levels of EPO were major determinants of FGF23 levels, to a greater extent than more established determinants such as renal function and serum calcium, PTH, and phosphate." (PMID 31170159, 2019). "Although iron deficiency and inflammation are known determinants of RDW as well as FGF23 metabolism, these factors only partly explained the association between RDW and FGF23." (PMID 26079688, 2015). "Moreover, new studies have shown that the simultaneous correction of iron deficiency and hyperphosphatemia in CKD reduces the magnitude of FGF-23 increase." (PMID 39911241, 2024). "In the subset of subjects with available iron parameters, upon further adjustment for the presence vs. absence of iron deficiency, the association between anemia and total FGF23 was attenuated." (PMID 37752381, 2024). "Importantly, we have shown that blocking FGF23 signaling stimulates red blood cell (RBC) production and rescues anemia, iron deficiency, and inflammation (chronic or acute)." (PMID 39666728, 2024). "Non-mineral factors, such as iron deficiency, Epo, and inflammation, affect FGF-23 production and metabolism." (PMID 39684548, 2024). "Additionally, iron deficiency (DFO-treated cells) caused significant upregulation of Tfrc mRNA and Fgf23 expression in both WT and Phd2-KO cells." (PMID 36650133, 2023). "Unlike iron deficiency and inflammation, where increased FGF23 production is coupled to increased cleavage, 1,25(OH)2D uncouples both mechanisms, thus leading to a net increase in iFGF23." (PMID 37681408, 2023). "Additionally, anemia and iron deficiency are strong inducers of EPO, and transgenic mice overexpressing EPO were found to have elevated FGF23." (PMID 35656701, 2022). "The role of hepcidin, a liver-derived acute phase protein that induces functional iron deficiency, as an intermediate metabolite in anemia, and iron-deficiency associated FGF23 upregulation is not yet well established." (PMID 35629904, 2022).